PRLR (prolactin receptor)
Diseases named in the same sentence as PRLR in open-access papers (continued):
Sharing a sentence is not in itself a finding about the gene and the disease.
prostate carcinoma (continued). "Additionally, the interaction between PRLR and the androgen receptor plays a critical role in the progression of prostate cancer." (PMID 40978029, 2025). "Lastly, Δ1-9-G129R-hPRL treatment prevented early stages of prostate carcinogenesis by inhibiting STAT5 phosphorylation, proliferation, abnormal basal-cell pattern and grade of intraepithelial prostate neoplasia suggesting the application of PRLR-based therapies in prostate cancer." (PMID 36714582, 2022). "Prolactin receptor (PRLR), which has been suggested as a therapeutic target in subgroups of breast and of prostate cancer, was overexpressed in EGFR-positive tumors compared to ALK/EGFR-negative tumors and compared to ALK-positive tumors (FC = 3.8, p = 0.0004 and FC = 2.6, p = 0.013)." (PMID 34125345, 2022). "Prolactin receptor (PRLR), which was suggested as a therapeutic target in subgroups of breast and of prostate cancer, was overexpressed in ERRB2-Ex20mut and EGFR-Ex18/19/21mut tumors compared to EGFR/ERBB2wt tumors (FC = 8.2, P = 0.00028 and FC = 4.3, P = 0.0012)." (PMID 34487971, 2021). "Bioinformatics analysis was then performed to assess the relationship between the expression levels of PRLR, JAK2, and STAT3 genes and the survival of prostate cancer patients." (PMID 40978029, 2025). "Given the pivotal role of PRLR and JAK2/STAT3 signaling in hormone - dependent cancers, exploring their regulatory mechanisms in prostate cancer is vital for developing new treatments." (PMID 40978029, 2025). "The eCBs, AEA and 2-AG, and the sCB, HU-210, inhibit the proliferation of human breast and prostate cancer cells via crosstalk between the CB1R, the high-affinity nerve growth factor receptor (NTRK1) and the prolactin receptor (PRLR) signalling pathways." (PMID 32340151, 2020). "In previous work, we had observed that the selective prolactin receptor modulator, S179D PRL, sensitized prostate cancer cells in vitro to physiological concentrations of calcitriol through an ability to increase expression of the vitamin D receptor." (PMID 33179012, 2020). "Investigating the regulatory mechanisms of PRLR and its downstream JAK2/STAT3 signaling axis in prostate cancer may provide a scientific foundation for the development of novel targeted therapies." (PMID 40978029, 2025). "However, clinical application of PRLR and JAK2/STAT3-targeted therapies for prostate cancer is still limited, partly due to severe side effects like immunosuppression and cytotoxicity." (PMID 40978029, 2025). "The results of a recent study suggested that extracellular PRL enhanced NSCLC cell proliferation and promoted JAK2/STAT3 signaling activity through GHR, but not PRLR as previously reported in breast and prostate cancers." (PMID 34487971, 2021). "GH can activate heterodimers consisting of the GHR and the prolactin receptor (PRLR) in breast tissue, activating PRL signaling pathways, and GHR-IGF-1R heterodimers may potentiate GH signaling in prostate cancer cells." (PMID 25580121, 2014). "Studies have shown that the expression of PRLR is not ubiquitous among prostate cancer cell lines, implying that the anticancer action of Osthole could be mediated through alternative pathways in addition to PRLR." (PMID 40978029, 2025). "However, whether Osthole exerts its effects via PRLR and JAK2/STAT3 signaling in prostate cancer remains unclear." (PMID 40978029, 2025). "However, to date, no studies have reported that Osthole can inhibit prostate cancer growth via PRLR." (PMID 40978029, 2025). "LFA102, a clinical-grade PRLR neutralizing antibody, failed to provide any clinical benefit in breast and prostate cancer patients, although insufficient dose exposure and inhibition efficacy in vivo might account for these negative results." (PMID 37208719, 2023).
prostate carcinoma (continued). "Although a phase I clinical trial with PRLR neutralizing antibodies (LFA102) in breast or prostate cancer patients showed no antitumor activity when used as monotherapy, a lot of studies supported the rationale of using this approach in chronic inflammatory diseases like rheumatoid arthritis." (PMID 34358244, 2021). "However, whether Osthole exerts its anticancer effects in prostate cancer by modulating PRLR and the JAK2/STAT3 signaling axis has not been thoroughly investigated." (PMID 40978029, 2025).
ovarian carcinoma (14 papers, 2013 to 2025). A malignant neoplasm originating from the surface ovarian epithelium. "The prolactin receptor (PRLR), a key member of the growth hormone receptor family, has been closely associated with hormone-dependent cancers such as breast and ovarian cancers." (PMID 40978029, 2025). "In brief, the use of a PRL antagonist peptide, G129R, was shown to block the PRL : PRLR signaling axis in ovarian cancer mouse models." (PMID 36714582, 2022). "This study investigates effects of prolactin (PRL) on ovarian cancer cells, analyzes PRL receptors (PRLR) in tissue micro arrays and relates PRLR expression to survival of ovarian cancer." (PMID 34358244, 2021). "Currently, a few viable targets, including the folate receptor and prolactin receptor, have emerged for optical imaging in ovarian cancer." (PMID 32185134, 2020). "We also found an association between extensive PRLR levels and extensive HCMV protein expression levels in tissue specimens obtained from ovarian cancer patients." (PMID 32121009, 2020). "In this study, HCMV’s effects on PRL and PRLR expression were assessed in infected ovarian cancer cells (SKOV3) by PCR and Western blot techniques." (PMID 32121009, 2020). "Tissue specimens obtained from 10 patients with ovarian cancer demonstrated high expression of PRLR, HCMV-IE, and pp65 proteins." (PMID 32121009, 2020). "In conclusion, PRL and PRLR were induced to high levels in HCMV-infected ovarian cancer cells and PRLR expression was extensively detected in HCMV-infected ovarian tissue specimens." (PMID 32121009, 2020). "More recently, prolonged treatment with hPRL-G129R in ovarian cancer models was found to antagonize the signaling activities of the prolactin/PRLR tumoral axis and to inhibit tumor growth by inducing destructive autophagy." (PMID 33335078, 2020). "Further in vitro studies have shown that the Prl/PrlR axis is active in some ovarian cancer cell lines to promote proliferation, cell migration and survival." (PMID 31063493, 2019). "Increasing evidence suggests that signaling through the prolactin/prolactin receptor axis is important for stimulation the growth of many cancers including glioblastoma multiforme, breast and ovarian carcinoma." (PMID 31063493, 2019). "For example, in the three ovarian cancer cell lines, expression of total prolactin receptor is high in TOV-112D, modest in OV-90 and low in the TOV-21G." (PMID 28422740, 2017). "Highly induced PRL and PRLR by HCMV infection may be of relevance for the oncomodulatory role of HCMV in ovarian cancer." (PMID 32322296, 2020). "Expression of the PRLR that belongs to the cytokine receptor family is for unknown reasons high in ovarian cancer." (PMID 32121009, 2020). "Highly induced PRL and PRLR by HCMV infection may be of relevance for the oncomodulatory role of this virus in ovarian cancer." (PMID 32121009, 2020). "We therefore hypothesized that HCMV may affect the PRL/PRLR axis in ovarian cancer." (PMID 32121009, 2020). "In the present study, we found evidence that HCMV infection can enhance the expression of PRLR and induce the production of PRL in ovarian cancer cells." (PMID 32121009, 2020). "HCMV induces high levels of PRL and PRLR transcripts and proteins in HCMV-infected ovarian cancer cells." (PMID 32121009, 2020). "Ovarian cancer tissue specimens from 10 patients were examined for expression of HCMV-IE, pp65, and PRLR." (PMID 32121009, 2020). "The expression of PRLR was very abundant in all ovarian cancer samples, except for one from a patient who was negative for HCMV and this patient only had focal expression of PRLR in her tumor specimen." (PMID 32121009, 2020). "Even in ovarian cancer, Beclin-1-independent autophagy has been reported in the context of non-canonical stimuli such as arsenic trioxide and prolactin receptor antagonism." (PMID 26239434, 2015).
ovarian carcinoma (continued). "Our data indicate a previously not recognized role for HCMV to regulate the PRL/PRLR system that may be of significance for the oncomodulatory role of HCMV in ovarian cancer." (PMID 32121009, 2020).
gestational diabetes (9 papers, 2017 to 2024). Carbohydrate intolerance first diagnosed during pregnancy. "Human in vitro islet studies demonstrated that beta cells replicate in response to prolactin (PRL), and the epidemiological study reported that PRLR SNPS are associated with gestational diabetes." (PMID 35204716, 2022). "Prolactin receptor (PRLR) signaling is one of the primary mediators of beta cell expansion during pregnancy, and loss of PRLR signaling results in reduced beta cell mass and gestational diabetes." (PMID 33633812, 2021). "Constitutively active PRLR in mouse beta cells stimulates beta cell replication and increases beta cell mass; conversely, insufficient lactogenic signaling by loss of PRLR restricts the capacity of beta cells to expand during pregnancy resulting in gestational diabetes." (PMID 35204716, 2022). "Transgenic mice with a specific deletion of PRLR from β-cells exhibit reduced β-cell expansion during pregnancy, leading to the development of gestational diabetes." (PMID 32316284, 2020). "In addition, some changes in the molecular structure of PRLR gene 5′ UTR and the promoter region were found to be associated with a 2.36-fold higher risk of gestational diabetes." (PMID 32316284, 2020). "Moreover, loss of PRLR signaling in β-cells causes gestational diabetes mellitus (GDM) in mice." (PMID 30174608, 2018). "Lactogens signal through the PRLR to stimulate pancreatic β-cell proliferation and insulin levels in vitro and in vivo, and the specific deletion of the PRLR in pancreatic tissue and in β-cells leads to failure to expand β-cell mass during pregnancy and to gestational diabetes." (PMID 33746901, 2021). "On the other hand, deletion of the MafB gene from β-cells, or deletion of the prolactin receptor which was shown to transcriptionally control MafB, resulted in a failure of adaptive expansion of β-cell mass during pregnancy, and the development of gestational diabetes." (PMID 28753672, 2017). "Also, mice lacking the PRLR in the pancreas and specifically in β-cells, develop gestational diabetes." (PMID 33746901, 2021). "Moreover, pregnant mice lacking PRLR in β-cells develop gestational diabetes, and STZ diabetic mice lacking PRLR showed increased intensity and frequency of hyperglycemia, decreased pancreatic islet density, β-cell proliferation, survival, and circulating insulin levels." (PMID 39045459, 2024).
glioblastoma (8 papers, 2013 to 2023). The most malignant astrocytic tumor (WHO grade IV). "Our previous study in glioblastoma demonstrated increased PRLR expression levels and indicated some efficacy to reduce tumor cell growth by using PRLRA in experimental systems." (PMID 32121009, 2020). "Treatment with the ES + Tum-combination activates the PRLR pro-proliferative pathway in glioblastoma." (PMID 24257371, 2013). "have studied the effects of PRLR inhibition on glioblastoma multiforme (GBM) pathogenesis." (PMID 36714582, 2022). "We therefore speculate that HCMV is a driving force for disease progression of glioblastoma via many different pathways including the PRL/PRLR axis." (PMID 32121009, 2020). "Although prolactin (PRL) and its receptor (PRLR) have been detected in glioblastoma multiforme (GBM), their role in its pathogenesis remains unclear." (PMID 31862900, 2019). "In glioblastoma multiforme (GBM), PrlR is often over-expressed, and over-expression is more common in patients with a more severe disease compared to patients with a less severe disease." (PMID 31063493, 2019).
Obesity (8 papers, 2014 to 2024). Accumulation of substantial excess body fat. "Along this line prolactin receptor deficient (PRLR−/−) mice are resistant to obesity under high fat diet due to increased energy expenditure." (PMID 24667351, 2014). "Other molecules suppressed by NP-6A4 include TCK1 and Prolactin receptor, however their potential roles in cardiac functions in conditions of obesity and pre-diabetes are yet to be elucidated." (PMID 34220518, 2021). "The relative resistance to HFD-induced obesity was accompanied by a more favorable carbohydrate homeostatic profile in PRLR−/− mice, consistent with the major implication of PRL signaling in energy balance." (PMID 24667351, 2014). "The positive effect of leptin inhibition on trabecular bone fraction and weight gain in diet-induced obesity resistant PRLR−/− mice, suggests that leptin and PRL signaling pathways are acting separately from each other." (PMID 24667351, 2014). "An unexplored but promising therapy is the clinical use of prolactin since administration with prolactin or prolactin-releasing peptide evidently improves steatosis in mice obesity models, and ablation of prolactin receptor increases hepatic triglyceride accumulation." (PMID 35860276, 2022). "As a proof of concept, PRL treatment in mice and rats with streptozotocin (STZ)-induced diabetes or diet-induced obesity improves their metabolic profile, whereas PRLR null mice with STZ-induced diabetes or diet-induced obesity show a more severe disease phenotype." (PMID 36213259, 2022). "Recently, we showed that lack of PRLR causes resistance to high fat diet-induced obesity due to enhanced energy expenditure and increased metabolic rate." (PMID 24667351, 2014). "The PRLR is present in AT from rodents and humans and PRL is secreted by human AT, while obesity decreases PRL release from human fat." (PMID 36213259, 2022). "We demonstrated earlier that despite increased food intake in both chow diet and high fat diet (HFD), PRLR−/− mice remained leaner than controls and were protected against HFD-induced obesity with a marked reduction in adiposity." (PMID 24667351, 2014). "We conclude that sulpiride reduces obesity-induced hyperglycemia by mechanisms that are independent of prolactin/prolactin receptor activity." (PMID 38635745, 2024). "However, the rescue of human PL gene expression seen in women with obesity that develop GDM and are treated with insulin, is consistent with rescue of both lactogenic signaling via the prolactin receptor and related negative effects in the maternal brain." (PMID 33743677, 2021). "This is also true for Prolactin receptor and TCK1 (Creatine kinase, testis isozyme), two other molecules suppressed by NP-6A4 treatment since their roles in cardiac functions in conditions of untreated obesity and pre-diabetes are not known." (PMID 34220518, 2021).
Infertility (7 papers, 2006 to 2024). "Novel strategies in the treatment of endometriosis-related infertility, based on its connection with prolactin such as the use of prolactin receptor antibodies and prolactin receptor antagonists, are under investigation, but adequate clinical studies have yet to be undertaken." (PMID 39407928, 2024). "Hence, the improvement of the deubiquitination level of PRLR in patients with HPRL is the key for the treatment of infertility, miscarriage, irregular menstruation and so on." (PMID 34424219, 2021). "In the current study, we hypothesized that BSZY-D could improve the HPRL infertility through PRLR deubiquitination, targeting JAK2/STAT5 pathway and its downstream kisspeptin of hypothalamus." (PMID 34424219, 2021). "Interestingly, when mammary tissue from prolactin receptor knockout (PrlR-/-) mice is transplanted into wild-type cleared fat pads, due to issues of infertility, mammary gland proliferation and differentiation are impaired." (PMID 27099931, 2016). "Similarly, PRLR-/- female mice are infertile, despite regularly mating every 3-4 days, in comparison to wild-type animals that mated every 12 days." (PMID 27901187, 2016). "Despite the reproductive defects exhibited by mutant females, PRL-/- male mice are fully fertile, and most PRLR-/- males are fertile, which demonstrates that the infertility in knockout females is caused by the lack of prolactin’s luteinizing effects." (PMID 27901187, 2016). "BSZY-D was involved in the deubiquitination of PRLR, which contributes to alleviating the symptoms of HPRL infertility." (PMID 34424219, 2021). "In addition, a loss-of-function PRLR mutation His188Arg mutation (H188R), which is located in the ECD and abolishes JAK2/STAT5 signaling, has been reported to occur in one family with autosomal dominant hyperprolactinemia (OMIM #615555) and to be associated with oligomenorrhea and infertility." (PMID 30445560, 2019). "Also, the activated deubiquitinating enzyme CSN5 could increase the expressions of JAK/STAT5 and kisspeptin via inducing the deubiquitination of PRLR, thereby alleviating the clinic manifestations of HPRL infertility." (PMID 34424219, 2021). "Of note, mammary gland development upon pregnancy could not be observed in PRLR-/- female mice, as well as in global double STAT5a/b knockout females due to their infertility." (PMID 27901187, 2016).
pancreatic cancer (7 papers, 2020 to 2024). "Although targeting PRLR with chemotherapy may cause complications with pregnancies and lactation, these factors pose little risk regarding most pancreatic cancer patients, due to the average age of diagnosis occurring over the age of 71." (PMID 38464736, 2024). "However, due to the widespread expression of PRLR within tissues, aberrant activation of this signaling has been linked to progression of prostate, breast, cervical, ovarian, and pancreatic tumors." (PMID 36714582, 2022). "In our own studies with pancreatic cancer, we observed that PRLR signaling potentiated invasive cell behavior and stemness through JAK2/STAT3 and ERK phosphorylation." (PMID 36714582, 2022). "The authors observed 3-4 times greater prolactin levels in women with PDAC, which led us to investigate the role of PRL and PRLR in pancreatic cancer." (PMID 36714582, 2022). "We found that, compared to PRLR-LF, PRLR-SF is predominantly expressed in pancreatic tumors of the KPC mice, the mouse PDAC cell line (Panc02) and the human PDAC cell lines (AsPC-1, BxPC3, CFPAC-1, and Patu8988)." (PMID 33664869, 2021). "Tissue-resident macrophages expressing PRLR are able to promote fibrosis of the TME in cases of pancreatic cancer." (PMID 33392181, 2020). "Moreover, little is known about prolactin signaling via PRLR-SF or the contribution of this pathway to pancreatic tumor progression." (PMID 33664869, 2021). "We investigated whether pregnancy and lactation affect the expression of PRLR isoforms in the pancreas and pancreatic tumors of mice." (PMID 33664869, 2021). "In preclinical studies with pancreatic cancer, we identified a small molecule Penfluridol to inhibit PRL induced JAK/STAT activation by competitively binding to PRLR." (PMID 36714582, 2022). "In summary, we made the interesting observation that PRLR-SF signals induced via the NEK9-Hippo pathway reduce the expression of G6PD and TKT in the PPP and thereby reduce pancreatic tumor progression." (PMID 33664869, 2021). "To investigate the expression of the PRLR isoforms in PDAC cells, we designed primers to measure the expression of PRLR-SF and PRLR-LF in spontaneously forming pancreatic tumors from genetically engineered KPC mice and human PDAC cell lines." (PMID 33664869, 2021).